CD8A (CD8 subunit alpha)
Diseases named in the same sentence as CD8A in open-access papers (continued):
Sharing a sentence is not in itself a finding about the gene and the disease.
tumor (continued). "Together, these data show that CD8α ALN-1 acts as a potent cellular adjuvant that enhances accumulation, proliferation and activation of adoptively transferred tumor-specific CD8+ T cells in response to TAA encounter." (PMID 34772757, 2021). "In accordance with our flow cytometry data, CD8α ALN-1 facilitated trafficking of different T cell clones from the TDLN to the TME and enables their oligoclonal expansion at the tumor site." (PMID 34772757, 2021). "The infiltration of anti-tumor effector cells i.e., CD8+ T cells was analyzed using CD8A and CD8B as gene markers." (PMID 33276627, 2020). "This strategy has been reported to successfully increase CD8α+ DCs cross-presentation capacity and to enhance CTL responses, promoting tumor elimination, both in prophylactic and therapeutic contexts." (PMID 32075343, 2020). "CD8A, DOK2, CX3CR1, TYROBP, CXCL9, CD300LF, and IFNG were identified as significant DEGs between tumor samples with high and low CD200R1 expression." (PMID 32635224, 2020). "In a recent study the expression of a tumour-induced plasmablast-like B-cell signature (TIPB) was significantly correlated with the expression of CD8a signatures and the density of CD8 + cells." (PMID 31901949, 2020). "Data on the total tumor density, density in the tumor stroma and density in tumor epithelial areas of cells positive for CD4, FoxP3 and CD45RO were therefore collected from the CD8a-high cases of the U-CAN study population." (PMID 33153037, 2020). "In our previous work, RNA levels of CD8A and CD8B (markers of cytolytic T cells) in tumors from patients prior to initiating BRAFi therapy demonstrated a positive correlation with eventual tumor regression after treatment." (PMID 32528881, 2020). "In-flow cytometric data analysis of the tumor digest revealed significantly increases in the population of CD4+, and CD8a+ cells in the TME, compared to all individual treatment groups at 10 days post-treatment." (PMID 32326142, 2020). "Varying degree of lymphocyte infiltration was observed and tumor types were stratified into immunologically “hot” or “cold” tumors based on their numbers of CD4+ and CD8a+ cells 12,30-32." (PMID 31754392, 2019). "Immune status of a panel of seven subcutaneous syngeneic mouse tumor models was analysed by immunohistochemistry and flow cytometry with respect to their capacity to attract TILs, i.e. CD4+ and CD8a+ cells." (PMID 31754392, 2019). "The lowest numbers of CD4+ and CD8a+ cells were found in B16F10 (blue area), defined as a “cold” tumor, and intermediate T cell numbers were found in Renca and P815, although high CD4+ numbers were found in both models based on IHC score only." (PMID 31754392, 2019). "FFPE sections were macrodissected to enrich for tumor for quantitative assessment of CD274 (PD-L1), PDCD1LG2 (PD-L2), CD8A, and IRF1 by RT-qPCR multiplex mRNA panel." (PMID 31533832, 2019). "Reduced tumor and spleen uptake of 89Zr-DFO-CD8a was observed in CD8a+ depleted mice and the uptake was comparable with that of isotype control (89Zr-DFO-IgG2b) confirming specificity." (PMID 31754392, 2019). "This subset is truly specialized in cross-presentation and a similar subset in mice, Batf3-dependent CD8α+ lymphoid or CD103+ DCs, were shown to be crucial for the induction of antitumor T-cell responses and tumor control." (PMID 30999964, 2019). "The OS tumours OS04 and OS03, and BZ28 and BZ35 that had the highest CD8A gene expression, also had high expression of PD-1, Tim-3, LAG-3 and CTLA4, indicative of a complex dysfunctional state of the CD8 + TILs in these tumours." (PMID 30674975, 2019). "Using immunohistochemistry, we detected several CD8α+ T cells and CD57+ NK cells at tumor sites in urethane-induced lung tumor tissues." (PMID 31275318, 2019). "Using flow cytometry, the expression level of CD2 and CD8α in γδ T cells was evaluated in both PBMC and tumor samples." (PMID 29930558, 2018).
tumor (continued). "Rejection of the irradiated and abscopal TSA tumours in mice treated with 8GyX3+anti-CTLA4 was abrogated in Batf3−/− and interferon-α/β-receptor-1 (IFNAR1)−/− mice, demonstrating the requirement for CD8α+ TIDCs responsive to IFNβ." (PMID 28598415, 2017). "One such study utilized a targeted PLGA nanoparticle to codeliver a model tumor antigen ovalbumin (OVA) and αGalCer to DEC205+ CD8α+ DCs." (PMID 29109728, 2017). "We chose to re-derive immune signature marker sets directly from TCGA tumor data using a handful of sentinel markers (FOXP3, CD8A, CD19, etc.)for immune cells and utilizing mutual rank distance metrics to expand the local gene expression neighborhoods." (PMID 28749946, 2017). "CD11c+CD8α+ dendritic cells cross present tumor antigens in the context of MHCI and costimulatory molecules to potently activate CD8+ T-cell immunity to cancer." (PMID 28910406, 2017). "Except the polarization of Th1 responses, maturation of DCs, in particular of the CD8α+ DCs, is also positive to CTL-mediated anti-tumor immunity." (PMID 28445973, 2017). "To create a library of possible R9F-specific clones, we vaccinated three C3 tumor bearing mice with DPX-R9F and purified the R9F-specific CD8α+ T cells from the spleens 8 days later using FACS; purity of the R9F-specific population was on average 85 %." (PMID 27777777, 2016). "Importantly, Ptgs1/Ptgs2−/− tumors were able to grow in Rag1−/−, Tap1−/−, and Batf3−/− hosts, indicating that prostanoid deficiency did not impair tumor formation in a cell-intrinsic fashion but rather acted to prevent CD8α+/CD103+ DC-dependent rejection mediated by CD8+ T lymphocytes." (PMID 26343581, 2015). "To determine which cell type(s) were responsible for anti-tumor responses in IL-15 TG/MT mice, we performed long term antibody depletion experiments with anti-NK1.1 or anti-CD8α antibody in IL-15 TG/MT mice." (PMID 25879689, 2015). "In contrast, tumor-infiltrating CD4+CD8α-, CD4-CD8α- and plasmacytoid DCs contained higher lipid levels in large tumors than small tumors." (PMID 25886502, 2015). "Similar reductions in the percent of CD8α+CD4- DCs were seen in the dLN of large tumor-bearing mice and in the spleens of small and large tumor-bearing mice." (PMID 25886502, 2015). "The anti-tumor effect was elicited by DC activation and then the infiltration of CD4+ (helper) and CD8a+ (cytotoxic) T cells into tumors." (PMID 25013909, 2014). "Such memory cells were verified by the fact that CD4+ cell depletion in vivo almost completely inhibited the anti-tumor effect, which was similar to CD8a+ or dual CD4+/CD8a+ cell depletion." (PMID 25013909, 2014). "Because CD8α+CD11c+ cDCs are highly specialized in cross-priming CTL response, tumor vaccine has been designed to mainly target this DC subpopulation." (PMID 24911024, 2014). "Considering the mean quantile of expression versus other probes, surface markers CD64, CD1D, CD14, CD33, CD8A, CD16b, CD45 maintain a low level in cell lines versus microdissected tumor (all lower than the 35th quantile, p)." (PMID 25380171, 2014). "In the second component, CGS 2 (C1QB), CGS 19 (GZMB), CGS 31 (CD8A) and CGS 34 (CD3E) correlated (R2>0.25) with the tumor cell content or its counterpart, i.e., the amount and function of bystander cells." (PMID 24223701, 2013). "Recent work demonstrated the crucial role of CD8α+ DC in the natural mechanisms of cancer immunosurveillance through response to endogenous type I IFN and induction of CTL-mediated tumor rejection." (PMID 23616948, 2013). "In an effective anti-tumor response sensing of the tumor by a separate DC subset drives type I IFN production, which is required for CD8α+ DC cross-priming of T cells." (PMID 21281484, 2011). "Consistently, tumor-bearing animals treated with either BCG or rBCG-LTAK63 displayed increased frequencies of CD8α+ dendritic cells in both spleen and tumor compared with untreated controls (data not shown)." (PMID 41522339, 2026).
tumor (continued). "Consequently, the CD8a/FoxP3 ratio was elevated in Axl KO tumors, although this was only statistically significant in MOC2-398, indicating a shift towards a more anti-tumor immune profile." (PMID 40149328, 2025). "For example, while normal tissue pericytes and T‐cell signaling included several MHC‐I to CD8A/CD8B receptors, those decreased in the tumor while fibronectin and collagen signals increased, suggesting a reduced antigen presentation ability of pericytes in the tumor." (PMID 40674254, 2025). "Moreover, our spatial transcriptomic analysis demonstrates that in LIHC tumour tissues, GMIP spatially overlaps significantly with the CD8+ T cell markers CD8A and CD8B." (PMID 40275529, 2025). "These correlations were moderate to strong as observed in the TCGA-COAD RNA-seq cohort (CD274 vs. PTGS2, R = 0.48; CD8A vs. CD274, R = 0.67) and similar when validated in the E-MTAB-12,862 cohort, comprising over 1,000 CRC tumor samples (CD274 vs. PTGS2, R = 0.47; CD8A vs. CD274, R = 0.61)." (PMID 40958118, 2025). "In this model, we examined tumour-resident T and B cells, which were labelled through the in vivo administration of non-depleting fluorescent-tagged antibodies (CD3-AF488 for T cells, CD8a-PE for cytotoxic T cells, B220-AF647 for B cells)." (PMID 39880930, 2025). "Researchers found that SEMA6D is predominantly expressed by non-hematopoietic cells, especially tumor cells, and shows a strong negative correlation with CD8A, PDCD1, IFNG and GZMB." (PMID 41438751, 2025). "However, a positive correlation was observed between circGRAMD4 and CD8+ T-cell infiltration in the TME based on WGCNA analysis and immunofluorescence staining of CD8A in tumor tissue slices from RCC patients." (PMID 40373256, 2025). "Furthermore, gene expression analysis of the TCGA-BRCA dataset indicated a significant reduction in CD8a expression within the high-IRRS group, suggesting a diminished cytotoxic CD8+ T cell response, which is critical for anti-tumor immunity." (PMID 40427728, 2025). "This aligns with biological expectations, as CD3 and CD8a are expressed on T cells but not on endothelial (CD31) or tumour (gp100, MelanA) cells." (PMID 40842484, 2025). "The EOMES GRN, encompassing CD8A, GZMK, STAT5A, CXCR3, and LAG3, integrates cytotoxic effector functions, migratory capacity, and checkpoint regulation—features critical for sustained anti-tumor immunity." (PMID 40520886, 2025). "In addition, we stained for tumor infiltrating lymphocytes (TILs): CD4+ T helper cells, CD8a+ CTLs, and B220+ B cells." (PMID 39808498, 2025). "Additionally, IHC revealed that the combination of anti-PD-1 and PRMT5i synergistically reduced Ki-67 levels in Renca tumor cells while increasing markers of tumor-infiltrating immune cells, including CD3, CD8a, and granzyme B." (PMID 40756764, 2025). "TIIC-related markers, including CD3, CD8a, and GZMB, represent T-cell killing of tumor cells." (PMID 39781264, 2025). "Notably, the enhanced cytotoxic activity (CD8A, CD8B, and NFKB1) observed in irradiated T cells suggests a potential mechanism contributing to the improved tumor control observed in our study." (PMID 39445067, 2024). "Correlation analysis showed that B. thetaiotaomicron abundance positively correlated the RNA level of CD8A, GZMB, IFN-gamma and TNF, which represented the function of cytotoxic CD8+ T cells, which is essential immune cells for Immune surveillance of tumor cells." (PMID 38270111, 2024). "Recent studies have highlighted the importance of CD8a+ DCs and tumor-resident CD103+ DCs in antitumor immunity due to their ability to secrete chemokines such as CXCL10, which recruit T cells to the tumor, and cytokines such as IL-12 to enhance the type I inflammatory state of infiltrating T cells." (PMID 37917174, 2024). "Three genes, CD8A, CRTAM, and EOMES, were consistently upregulated in all six tumor types." (PMID 38488909, 2024).
tumor (continued). "Furthermore, we observed a high expression of CD8 (a marker of CD8+ T cells) and CD68 (a marker of macrophages) in NAT, while their presence was almost undetectable in the tumour." (PMID 38804617, 2024). "Furthermore, the inflammation promoted by Th17 enhances the presentation of tumor antigens by CD8α+ DC to CD8 cells, thus enhancing the anti-tumor response." (PMID 38690280, 2024). "Importantly, the difference in tumor growth between the Ctrl and Stk24 KO groups disappeared after anti‐CD8α mAb treatment, indicating that STK24 supports CT26 tumor development through inhibition of CD8+T cell‐dependent cytotoxic T cell responses." (PMID 38229183, 2024). "Both increased CD8a and HLA-A expression negatively correlated with PRKDC expression, suggesting that decreased DNA-PK expression and activity may promote CD8 tumor infiltration." (PMID 39436696, 2024). "For instance, FLI1 in myeloid cells activated MHC-II molecules’ expression, which mainly improved the tumor antigen presentation, but in the T cells, FLI1 inhibited CD8A expressions, which might harm T cell activation." (PMID 38448802, 2024). "Specifically, the subset of dendritic cells that are CD8α+ appears to be important for mediating this effect, as these cells perform antigen cross presentation and priming of CD8+ T-cells, which are responsible for the cytotoxic anti-tumor immune response." (PMID 38659582, 2024). "Interestingly, for CD4 and CD8α the average intensity/cell is consistently lower in 4T1 and B16F10 tumor models relative to the CT26 tumor model." (PMID 38605049, 2024). "In addition, we observed that the expression of CCL5, CD8A, and PD1 in the tumor tissue of mice in the combination therapy group was significantly higher than that in the control group, a result consistent with that of mIHC." (PMID 39183447, 2024). "Depletion of CD8 T cells in combination with IL-15:IL-15Ra complexes improved tumor control versus PBS/anti-CD8α Abs, consistent with a distinct NK cell and CD8 T cell contribution to anti-tumor responses." (PMID 38267402, 2024). "Moreover, we found a significantly higher positive regression coefficient between CD8A expression and TNF‐α or LTβ in adjacent tumour tissues than in HCC tissues and normal tissues." (PMID 37997519, 2023). "In addition to MCC tumor cells, we observed clusters of immune cells including CD4-positive and CD8A-positive T cells (clusters 7 and 11) and CD68-positive macrophages (cluster 16)." (PMID 36719743, 2023). "Tumours with a low MITF expression showed an increase in the numbers of CD3D (p = 0.048), CD8A (probe 3: p = 0.01), and CD68 (two probes, p = 0.001 and p = 0.004) cells, as well as a higher expression of HLA-A (three probes: p = 0.003, p < 0.001, and p = 0.002) and HLA-B (p = 0.004)." (PMID 37240204, 2023). "In this study, we observed that SPA was enriched for type I tumor immune microenvironment (PD-L1+/CD8A+) as compared with Non-SPA." (PMID 36845145, 2023). "As expected, we observed that SPA had a higher proportion of type I tumor immune microenvironment (PD-L1+/CD8A+) than Non-SPA, indicating adaptive immune resistance in SPA." (PMID 36845145, 2023). "In agreement with this possibility, pre-feeding of the MR diet increased the growth of B16.F10 melanoma tumours subcutaneously grafted in WT C57BL/6J mice but not in CD8a knockout C57BL/6J mice." (PMID 37537369, 2023). "As assessed by acoustic force microfluidic microscopy evaluating the cellular binding avidity between the CD70 specific CAR T cells and AML tumor cells, CD70 specific CARs with the CD8α hinge conferred augmented binding avidity on T cells as compared to CD27 hinge CARs." (PMID 38090558, 2023). "Because Vγ7+ IELs express CD8αα dimers, whereas most other intestinal γδ T cells do not, we used CD8α as a marker to specifically quantify the Vγ7+ cell representation in tumor-bearing VA and VAK mice." (PMID 37309673, 2023). "cDC1s, expressed XCR1, CD8a, CLEC9A, CD103, and IRF8, are essential for anti-tumor immunity." (PMID 38012715, 2023).
tumor (continued). "Moreover, Fn infection reduced the αPD-L1-mediated increase in the CD4+, CD8a+ and GZMB+ CD8a+ T-cell populations in the tumor region." (PMID 37723150, 2023). "Given the complexity of the tumor microenvironment and the fact that both tumor‐intrinsic and microenvironmental activities regulate anti‐tumor immunity, it may be challenging to correlate ANGPTL2 mRNA levels with those of CD8A." (PMID 37452654, 2023). "Analysis of representative genes showed that the expression of CD8a and IFN-γ genes was significantly increased while the expression of Csf1r in CD45+ tumor-infiltrating immune cells was significantly reduced in TCh3 anti-PD-L1 group compared with other groups." (PMID 35366939, 2022). "Among them, the expression levels of CD8A, CD8B, GZMA, GZMB, and PRF1 were used to evaluate the infiltration levels of tumor cytotoxic T lymphocytes (CTLs), and a high-CTL-infiltration group has been related to significantly prolonged survival time of patients receiving immunotherapy." (PMID 36405701, 2022). "Likewise, most ICD-related genes, including IL-6, IL-10, NLRP3, CD8A, CD8B, and TLR4, exhibited attenuated expression levels in tumor cells compared to normal cells." (PMID 36225939, 2022). "Bioinformatic analyses reveal that AGO2 expression is negatively correlated with the mRNA levels of CD3, CD8A, and GZMA in a variety of TCGA human tumor types, indicating AGO2-low tumors have a higher abundance of total and CD8+ T cells and stronger immune cytotoxic activity." (PMID 36323669, 2022). "ST analysis confirmed CD8+ cell infiltration in MPC prostate with 9.1–95.5% of CD8A+ positive spots overlapping with FOLH1+ spots, indicating the proximity of effector T-cells and PSMA-expressing cancer cells in the tumour tissue." (PMID 36243890, 2022). "This tumor growth stasis response is likely mediated by other tumor-infiltrating immune cells, for example, NK cells, whose CPA-induced levels were further increased by CD8α T-cell depletion." (PMID 36187936, 2022). "Because the reactivity, ontogeny and cancer cell sensing mechanisms of αβILTCKs remained unknown, Chou and colleagues next compared paired-TCR sequences from tumour-resident NK1.1+CD8α+ αβILTCKs and conventional PD-1+CD8α+ T cells (PD-1+ T cells)." (PMID 35768418, 2022). "Indeed, IL-33 expression correlated strongly with CD8A and granzyme B as well as genes like BATF3, IRF8, THBD, CLEC9, and XCR1 that are required for tumor antigen cross-presentation functionality of CD103+ dendritic cells (DCs)." (PMID 36256464, 2022). "Similarly, vaccination with necroptotic cancer cells was found to stimulate the cross-priming of cytotoxic CD8a+ T cells and to produce IFN-g ex vivo, generating a strong anti-tumor response." (PMID 35480307, 2022). "To survey for the presence of infiltrating immune cells in cancer tissue, we measured central immune cell markers (CD8a, CD11c, CD16 and CD68) simultaneously and categorized the present cohort into highly infiltrated (“hot”) tumor and lowly infiltrated (“cold”) tumor samples." (PMID 36139700, 2022). "Interestingly, all tumor types showed strong correlation between IDO1 expression and CD3E and CD8A expressions." (PMID 35780226, 2022). "Flow cytometric analysis at an interim timepoint (17 days after tumor inoculation) and study endpoint (25 days after tumor inoculation) confirmed depletion of CD3+CD8+ T cells in the spleens and tumors of CD8α-treated mice compared to IgG2B isotope-treated control." (PMID 36686775, 2022). "Next, we employed lineage-specific markers to annotate clusters into major cell types of the tumor, including T cells (CD3G, CD4, CD8A, CD28, and IL7R), B cells (CD19 and CD20), myeloid cells (HLA-DRA and CD14), fibroblasts (THY1 and ACTA2), and tumor cells (EPCAM and S100A)." (PMID 35634306, 2022).